KL (klotho)
Diseases named in the same sentence as KL in open-access papers (continued):
Sharing a sentence is not in itself a finding about the gene and the disease.
kidney disease (146 papers, 2012 to 2026). "Renal tubular-specific depletion of klotho is associated with a predisposition to renal fibrogenesis, implicating epithelial klotho loss in renal disease progression." (PMID 40362638, 2025). "We demonstrated that, in the setting of CKD, along with the classic features of renal disease, there is a decrease in cognitive abilities, which appear to be associated with a marked reduction in the expression of Klotho in the cerebral cortex." (PMID 38673780, 2024). "In the context of kidney disease, klotho deficiency has been linked to accelerated progression of CKD, cardiovascular complications and higher mortality rates." (PMID 39281418, 2024). "Both this fact and the evaluation of a possible association of Klotho in heart diseases with concomitant kidney diseases should be of interest for future studies." (PMID 38787156, 2024). "In these early stages of kidney disease there is hardly any loss of tubular cells to justify the decrease in Klotho, which is probably due to the metabolic and hemodynamic stress that occurs during diabetic disease." (PMID 37686263, 2023). "In the early stages of renal disease, a reduction in the co-receptor klotho can lead to an increased risk of vascular calcification and vascular senescence." (PMID 37143722, 2023). "Systemic or local renal inflammation decreases Klotho expression in the kidney, and most kidney disorders are associated with a decline in circulating levels of Klotho mRNA and Klotho expression in the kidney." (PMID 37928907, 2023). "Only if regulatory mechanisms are better understood, potential strategies can be developed to increase the Klotho level for the treatment of kidney diseases with Klotho deficiency." (PMID 35299661, 2022). "Experimental models have already reported that development and progression of kidney diseases were significantly associated with a decline in Klotho." (PMID 35656176, 2022). "There is some evidence of Klotho deficiency and the occurrence of kidney disorders in animal models and in humans." (PMID 36555091, 2022). "There is increasing evidence that the source of circulatory sKlotho is derived from the kidney, indicating the close association between Klotho and kidney diseases." (PMID 36210812, 2022). "As a result, Klotho deficiency makes the kidney vulnerable to various insults, thus contributes to the progression of kidney diseases." (PMID 35299661, 2022). "Klotho deficiency significantly reduces lifespan, and its overexpression extends it and protects against various pathological phenotypes, especially renal disease." (PMID 33478014, 2021). "As addressed here, Klotho overexpression has renoprotective effects, whereas its downregulation is associated with the progression of kidney diseases." (PMID 35056905, 2021). "Loss of Klotho is a common finding after kidney injury, which plays a pathogenic role in the onset and progression of kidney disorders." (PMID 33362554, 2020). "As Klotho functions in phosphate retention, loss of Klotho increases serum phosphate levels, accelerating aging and age-related cardiovascular and renal diseases in mice and humans." (PMID 31226747, 2019). "The Klotho protein can induce antioxidant enzymes, and Klotho deficiency is associated with increased oxidative stress, even in experimental models of kidney disease or in dialysis patients." (PMID 28129785, 2017). "Emerging evidence suggests α-klotho deficiency is an early biomarker of kidney disease as well as a pathogenic factor." (PMID 25084095, 2014). "Also, lower klotho levels seem to be linked to stiff arteries and heart issues in people with kidney disease." (PMID 40559238, 2025). "Consequently, Klotho deficiency is suggested to be a prevalent characteristic of kidney disorders, playing a significant role in their etiology and progression, including CKD and its associated complications." (PMID 38792509, 2024).
kidney disease (continued). "In sum, all of this evidence supports the notion that the down-regulation of Klotho may play a role in the development and progression of CI associated with renal disease." (PMID 38673780, 2024). "It has been demonstrated that serum levels of klotho decrease with aging and it is also associated with several typical age-related disorders such as diabetes, vascular calcification, atherosclerosis, cardiovascular and renal diseases." (PMID 36674838, 2023). "Any therapy based on the administration, restoration, or stimulation of exogenous Klotho might provide a novel strategy for combating aging and age-associated diseases including kidney disease." (PMID 36829798, 2023). "Here, we demonstrated that a partial klotho deficiency that occurs with any evidence of renal disease, could have an added deleterious impact in the setting of AKI." (PMID 36674838, 2023). "Increasing evidence showed that a close association between Klotho and kidney diseases." (PMID 37560310, 2023). "At the clinical level, a decrease in klotho levels may be due to several causes, such as aging and being in the early stages of renal disease, which can remain as a silent disease for many years until it is clinically detected." (PMID 36674838, 2023). "Mice that exhibited Klotho deficiency presented a premature aging phenotype, whereas Klotho overexpression extended their lifespan by up to 30% and protected them against many pathological phenotypes, especially renal disease." (PMID 33478014, 2021). "Klotho deficiency is closely associated with kidney disease." (PMID 33767585, 2021). "Klotho, as an antioxidative, antifibrotic, and anti-inflammatory molecule, is highly expressed in distal tubular epithelial cells and is closely associated with kidney diseases." (PMID 32908633, 2020). "The significantly lower UrKl/Cr in dogs with progressed CKD and its correlation with various parameters reflecting either kidney function or the severity of kidney disease suggests that klotho is associated with CKD and the development of its clinical consequences in dogs." (PMID 32677951, 2020). "Thus, Klotho deficiency is a key early step in kidney disease progression and a crucial factor in the development of diabetic complications." (PMID 27668003, 2016). "In addition, Klotho deficiency promotes renal fibrosis in several kidney disease models." (PMID 39497615, 2025). "Therefore, increased serum IS levels and decreased Klotho protein levels are independent risk factors that may be used to treat kidney disease." (PMID 40119098, 2025). "An increasing number of studies are emerging that explore the use of Klotho and p21 expression in kidney biopsy tissue, plasma, and urine, and this may offer an opportunity to predict biological age in persons at high risk for kidney disease." (PMID 37892346, 2023). "Since its initial discovery, increased levels of klotho have been associated with longevity in several populations and decreased levels of klotho have been associated with aging-related diseases including cancer, cardiovascular disease, kidney disease, and recently neurodegenerative diseases." (PMID 36552155, 2022). "Lower levels of klotho protein are found in people with kidney disease; therefore, they act as a marker in CKD." (PMID 40559238, 2025). "To date, the cardioprotective effect of Klotho on cardiomyocytes has only been observed in conditions of uremic cardiomyopathy, as its expression is significantly reduced in renal disease." (PMID 39815421, 2025). "Both α and β Klotho are critical genes that control kidney homeostasis and aging and are considered ideal intervention targets for many renal diseases and even extrarenal complications." (PMID 40514411, 2025). "A report has shown that excessive production of Klotho rescued mice against kidney disease and longer their existence by approximately 30%." (PMID 40119098, 2025).
kidney disease (continued). "Diminished levels of the circulating hormone Klotho and anti‐ageing proteins from the sirtuin family, commonly observed in kidney disease, contribute to accelerated systemic ageing, as evidenced by human and animal studies." (PMID 39497615, 2025). "A notable decrease in Klotho mRNA and protein expression is observed in the majority of renal diseases, underscoring its sensitivity to pathological changes in the kidney." (PMID 40799848, 2024). "Klotho, a well-known anti-aging protein with reno-protective potential, is a promising remedy for kidney disease." (PMID 38164143, 2024). "Klotho has been postulated as a potential biomarker for the diagnosis and prognosis of kidney disorders and a therapeutic target 22-25." (PMID 38164143, 2024). "Despite the published literature highlighting the importance of klotho in kidney disease, significant gaps remain in our understanding of how klotho levels specifically influence prognostic outcomes in CKD patients." (PMID 39281418, 2024). "For example, the epigenetic dysregulation of Klotho in renal disease includes promoter methylation, histone acetylation, the action of transcription factors (TF) and miRNAs." (PMID 39272986, 2024). "In this study, we used databases and web resources (STITCH version 5) to demonstrate that PTX, ROS (H2O2), Klotho, and caspase 3 closely interact with renal disease-related pathways." (PMID 39765800, 2024). "Any treatment strategy that leads to an improvement in the Klotho levels by augmentation with external Klotho or uplifts the levels of endogenous Klotho manufacturing can be labeled a new novel therapy in renal disorders such as CKD." (PMID 37425590, 2023). "Many articles have dealt with other pathologies where Klotho proteins are thought to play significant roles, most prominently in renal diseases." (PMID 37958253, 2023). "These two studies are supported by many other reports showing glomeruloprotective effects of soluble Klotho in several kidney disease models." (PMID 36813870, 2023). "In patients with kidney disease, uremia raises oxidative stress and senescence in endothelial cells and it has been demonstrated that extracellular Klotho prevents the senescence of endothelial cells induced by oxidative stress." (PMID 36829798, 2023). "In recent years, Klotho, produced in the kidney, has gained attention as a potentially sensitive and specific biomarker in renal disease with cardiac complications." (PMID 38069366, 2023). "In T2DM subjects, the decrease in serum Klotho has been related with the progression of kidney disease even from the early stages." (PMID 37686263, 2023). "Research has shown that klotho promotes autophagy to alleviate kidney inflammation and impact the progression of kidney diseases." (PMID 38099142, 2023). "Specifically, Klotho was required to promote excessive FGF23 expression by long bones during kidney disease." (PMID 36967231, 2023). "Conversely, Klotho overexpression and treatment with recombinant protein have been demonstrated to be renoprotective in numerous animal models of kidney disease." (PMID 36813870, 2023). "Bone‐intrinsic autocrine or paracrine signaling of FGF23 via FGFR/Klotho was reported to be important for the FGF23 increase in experimental kidney disease." (PMID 36967231, 2023). "This underscores the therapeutic potential of Klotho-enhanced UDSCs in the treatment of kidney diseases." (PMID 38072946, 2023). "The first case study highlights the potential role of klotho as a drug target for aging and kidney disease, while the second study gathers knowledge regarding approval, usage, and safety for remdesivir, the first approved coronavirus disease 2019 therapeutic." (PMID 35368424, 2022). "Klotho downregulation can be both a consequence and driver of inflammaging and increased ROS production in kidney disease." (PMID 35204184, 2022).
kidney disease (continued). "In fact, many preclinical studies have elaborated restoration of epigenetic abnormality of Klotho expression provided new therapeutic performance for diverse etiologies of kidney diseases including CKD." (PMID 35299661, 2022). "Additional studies are needed to investigate the detailed crosstalk between Klotho and Calpain 1 in other renal disease models." (PMID 35155498, 2022). "Klotho is an anti-aging and anti-fibrosis protein that plays a crucial role in the physiology and pathophysiology of renal diseases." (PMID 35155498, 2022). "Existing evidence reveals that abnormal klotho levels are regarded as the earliest biochemical abnormality of kidney disease." (PMID 35820962, 2022). "On the one hand, the serum klotho protein level is one of the early markers of kidney diseases, as the level declines at the early stage of CKD and continuously decreases with the progression of CKD." (PMID 35436879, 2022). "The klotho (Kl–/–) and/or Fgf23 (Fgf23–/–) knockout mice exhibit many key aspects associated with human CAVD including, premature aging, kidney disease, increased serum phosphate levels (i.e., hyperphosphatemia), and increased osteogenic gene expression." (PMID 35928937, 2022). "Klotho usually seems to restore normal autophagy activity and treat disorders including neurodegenerative diseases and kidney diseases, suggesting the protective role of autophagy." (PMID 36338347, 2022). "Children with mild to moderate kidney disease had decreased serum Klotho levels at the beginning of the study, and this was normalized by Vitamin D treatment." (PMID 35903083, 2022). "The majority of kidney disorders feature enhanced inflammation concomitant with decreased Klotho expression." (PMID 35299661, 2022). "Taken together, these data reveal that Klotho can be used both as a biomarker and, potentially, as a therapeutic tool for renal diseases." (PMID 35056905, 2021). "This form of the protein was detected in both serum and urine, but reports of Klotho levels in these bodily fluids in renal disorders are rare and sometimes conflicting." (PMID 34360633, 2021). "Klotho is, in this way, an essential factor to be investigated in both the physiology and pathology of renal diseases." (PMID 35056905, 2021). "In terms of renoprotective effects, klotho deficiency has been found to intensify renal damage in experimental models of renal diseases, whereas klotho overexpression or the administration of klotho protein ameliorates it." (PMID 34673800, 2021). "Klotho has been identified as an antiaging gene that is primarily expressed in the kidney, parathyroid, and choroid plexus; decreased Klotho expression has been correlated with kidney disease." (PMID 32760286, 2020). "Klotho is a circulating anti-ageing hormone that predicts progression of cardiovascular and renal disease." (PMID 33225726, 2020). "The protein expression of Klotho was found to be decreased in kidney tissues in several clinical and animal studies on kidney disease, including DKD." (PMID 32908633, 2020). "We also found that Klotho expression was down-regulated with advancing renal disease, with sera from HD subjects virtually abolished its expression." (PMID 31519772, 2019). "Klotho, as a potential biomarker in renal disease, was decreased expression as the CKD progress and contribute to calcium and phosphorus metabolism." (PMID 30791885, 2019). "Overexpression of the Klotho gene or injection of KLOTHO protein shows beneficial effects in rodent models of various renal diseases." (PMID 31199854, 2019). "Unfortunately, little is known regarding the effect of ginsenoside components, except Rg1, on Klotho signaling in kidney diseases." (PMID 31400753, 2019). "In CKD, as the renal disease advances, a decline in Klotho expression has been reported whereas FGF-23 expression increases progressively; high serum phosphate and PTH and low vitamin D levels accompany these changes." (PMID 30370270, 2018).
kidney disease (continued). "The anti‐ageing hormone klotho promotes longevity and protects against cardiovascular and renal diseases." (PMID 27696667, 2017). "As soluble Klotho is easily detectable and a decrease in its level has shown significant correlations in early phases of cardiovascular and kidney diseases, it has gained attention as a potential early diagnostic marker for these diseases." (PMID 27668003, 2016). "Klotho protein declines early in renal patients and in experimental animals of various renal diseases, which limits its renal protective activities." (PMID 27703201, 2016). "The essential role of TGF-β1 and the protective effect of Klotho protein in pathogenesis of various renal diseases, including IgAN, have been documented in different clinical and experimental models." (PMID 27806690, 2016). "During kidney disease progression, there is reduced expression of Klotho, a finding also confirmed in our study." (PMID 25222475, 2014). "The majority of the research on Klotho has been conducted in vitro and in animal studies but there is emerging data from human studies which suggest that Klotho may be a modifiable factor involved in the pathogenesis of cardiovascular and renal disease in at-risk populations." (PMID 22121479, 2012). "Klotho, a protein that plays a crucial role in aging and metabolism, was reduced in aged mice kidney, which was consistent with its reduction with aging and kidney disease." (PMID 40585885, 2025). "We hypothesize that the reduction in serum Klotho levels associated with NSAID use may be related to the following mechanisms: Klotho protein is primarily expressed in the kidneys, and kidney disease can disrupt renal Klotho expression." (PMID 40309444, 2025). "Thus, kidney function is compromised in patients with kidney disease, OATs are downregulated, serum IS levels are steadily rising, and klotho protein levels fall." (PMID 40119098, 2025). "The well-known anti-inflammatory protein Klotho may have a renoprotective impact on kidney disorders by blocking the pyroptosis mechanism." (PMID 40119098, 2025). "Furthermore, PTX, ROS (H2O2), Klotho, and caspase 3 (CASP3, an apoptosis-associated protein) were closely associated with renal disease-related pathways." (PMID 39765800, 2024). "This study confirmed that Klotho was expressed in macrophages, monocytes and lymphocytes and exerted anti-inflammatory effects in these cells, which indirectly suggested that Klotho might be involved in regulating the inflammatory response in kidney disease." (PMID 38584258, 2024). "The down-regulation of the renal Klotho was reported in kidney diseases." (PMID 38540101, 2024). "The influence of Klotho on protective mechanisms was well-studied in several kidney diseases." (PMID 37985893, 2023). "Therefore, the activation of Nrf2 by Klotho seems to be an attractive therapeutic strategy against oxidative stress in kidney disease." (PMID 36829798, 2023). "Many previous studies have confirmed that klotho has negative regulatory effects and may be involved in a variety of conditions, such as altered cognitive function, metabolic disorders, kidney disease, and skeletal muscle reduction." (PMID 37587536, 2023). "According to other reports, Klotho, mostly expressed in renal tubular epithelial cells, protects the kidneys against acute and chronic injury, while lower levels were observed in patients with renal diseases." (PMID 37760798, 2023). "For therapeutic effects, Klotho supplementation to restore its levels in patients with kidney diseases may improve not only renal function but also fertility." (PMID 37759974, 2023). "Furthermore, klotho has the potential to serve as a promising biomarker for the prediction of aging, endocrine or renal diseases." (PMID 37143722, 2023). "In recent years, the role of Klotho in kidney disease has attracted increasing attention." (PMID 36829798, 2023).